ENSG00000288520 (novel protein)
Gene: Protein-coding gene on chromosome 6 (154,159,828 to 154,510,114, reverse strand). Ensembl gene ENSG00000288520.
Gene Ontology:
Molecular function: protein binding; protein-macromolecule adaptor activity
Biological process: positive regulation of cellular response to hepatocyte growth factor stimulus; enzyme-linked receptor protein signaling pathway; regulation of signal transduction
Cellular component: cytoplasm; membrane
Genetic constraint (gnomAD): Loss-of-function variants: 38 observed, 77.84 expected, observed/expected ratio (o/e) 0.49, 90% interval 0.38 to 0.64. Missense variants: 782 observed, 922.64 expected, observed/expected ratio (o/e) 0.85, 90% interval 0.8 to 0.9. Synonymous variants: 341 observed, 364.2 expected, observed/expected ratio (o/e) 0.94, 90% interval 0.86 to 1.02.